PTH (parathyroid hormone)
Diseases named in the same sentence as PTH in open-access papers (continued):
Sharing a sentence is not in itself a finding about the gene and the disease.
Kidney Disease (178 papers, 2007 to 2026). "PTH can be oxidized in patients with renal disease, and oxidation of PTH at methionine residues 8 and/or 18 results in loss of biological activity." (PMID 30627584, 2018). "High levels of serum calcium, phosphate, calcium–phosphate product, and parathyroid hormone (PTH) are associated with all-cause and cardiovascular-specific mortality in patients with kidney disease." (PMID 28973026, 2017). "In patients with renal disease, the condition is associated with increased levels of parathyroid hormone, calcium, and phosphorous." (PMID 28589153, 2017). "Deviations of serum concentration of phosphate (P), calcium (Ca) or parathyroid hormone (PTH) from the values recommended by KDIGO (Kidney Disease Improving Global Outcomes) are associated with a negative outcome." (PMID 26808154, 2016). "The CARI guidelines while recommending vitamin D therapy in early kidney disease for those with elevated PTH warn against the risk of vitamin D therapy in the face of elevated serum calcium and phosphate levels, which should be monitored regularly." (PMID 24451311, 2014). "Low serum calcium has been implicated in parathyroid hormone dysregulation and subsequent mineral bone disease, which could exacerbate kidney disease progression." (PMID 38769367, 2024). "In kidney disease, elevated PTH has been reported to preferentially cause cortical bone loss." (PMID 25886405, 2015). "Furthermore, recent studies indicate common aetiologies and mechanisms for certain medical illnesses, bone loss and osteoporotic fractures, and PTH and adipocytokines are important factors acting in bone, cardiovascular, metabolic and kidney diseases." (PMID 22333003, 2012). "Thus progression of kidney disease causes changes in phosphate homeostasis finally leading to a rise in serum levels of PTH which is called secondary hyperparathyroidism (sHPT)." (PMID 18266955, 2008). "Correlation analyses showed that cause of kidney disease (p = 0.03), kidney transplant status (p < 0.001), income (p = 0.02), serum calcium (p = 0.03), serum phosphate (p < 0.001), eGFR (p < 0.001), treatment center (p < 0.001), and furosemide use (p = 0.01) were potential determinants of PTH." (PMID 22867424, 2012). "Classification according to Kidney Disease: Improving Global Outcomes guidelines for intact parathyroid hormone and parathyroid hormone 1–84 assays, Johannesburg, South Africa, 06 April 2022 to 21 September 2022." (PMID 40937300, 2025). "We found that serum BUN was high in Ad mice in both groups indicating the presence of kidney disease while PTH was higher in 21-wk Ad vs. 12-wk Ad." (PMID 40408439, 2025). "SHPT was defined in accordance with the Kidney Disease: Improving Global Outcomes (KDIGO) 2017 guidelines as an intact parathyroid hormone (iPTH) level greater than nine times the upper reference limit in hemodialysis patients." (PMID 41492600, 2025). "BUN was high at both timepoints indicating the presence of kidney disease, while PTH was statistically higher at 21-weeks vs. 12-weeks." (PMID 40408439, 2025). "According to the Kidney Disease Outcomes Quality Initiative, the target PTH range for children receiving dialysis is 150–300 pg/mL." (PMID 39433982, 2024). "In multivariate approach limited to monotherapy patients, after correcting for age, underlying kidney disease, modality therapy duration, IDWG, serum parathyroid hormone, albumin, and blood hemoglobin, the effect of treatment choice remained significant." (PMID 38899176, 2024). "Kidney Disease Improving Global Outcomes (KDIGO) guidelines suggest measurements of serum PTH or specific ALP to evaluate bone disease as predictors of underlying bone turnover." (PMID 39310569, 2024). "All CKD mice in this study had elevated serum BUN indicating the presence of kidney disease as well as high PTH which matches our previous work with this model of CKD." (PMID 38856730, 2024).
Kidney Disease (continued). "iPTH tests accurately assess the activity of the parathyroid gland in patients with kidney disease and dialysis by measuring the active portion of the parathyroid hormone." (PMID 39202612, 2024). "The 2009 Kidney Disease Improving Global Outcomes (KDIGO) guideline suggests that PTH levels in dialysis patients should be maintained at two to nine times the upper reference limit (URL), while suggestions for CKD patients without dialysis are lacking." (PMID 39208984, 2024). "In this regard, it is noteworthy that KDIGO (Kidney Disease: Improving Global Outcomes) recommends measuring parathyroid hormone (PTH) and bone alkaline phosphatase (BALP) levels to monitor disease progression and pharmacological treatment." (PMID 36771305, 2023). "The PTH target range of the Kidney Disease Outcomes Quality Initiative guideline of 150 pg/mL–300 pg/mL was based on studies that used the Allegro iPTH assay, which is no longer available for standardisation." (PMID 37102048, 2023). "The Kidney Disease Outcome Quality Initiative guideline recommends withholding VDRAs if intact PTH levels are less than 150 pg/mL21." (PMID 36104443, 2022). "FGF-23 is a phosphaturic hormone that is elevated in the later stages of kidney disease, followed by a reduction in 1,25-dihydroxy-vitamin D (1,25 [OH]2D) and an increase in parathyroid hormone (PTH)." (PMID 36232497, 2022). "For example, male Cy/+ rats with a genetic progressive kidney disease, develop high parathyroid hormone (PTH), vascular calcifications, and cortical porosity, but females do not develop disease phenotypes even with ovariectomy." (PMID 33891630, 2021). "Abnormal calcium and phosphate levels and parathyroid hormone levels in kidney disease contribute to the phenotype switch of vascular smooth muscle cells to osteoblast-like cells and local inflammation, contributing to vascular calcification." (PMID 34218791, 2021). "It is well known that kidney disease leads to increased production of the parathyroid hormone and a build-up of phosphate in the body which, in turn, binds to Ca2+ and leads to brittle bones." (PMID 35011693, 2021). "Further studies are needed for the establishment of the reference intervals of the method in dogs and for better characterize the complex interactions between PTH and renal disease in a large population of spontaneously affected dogs." (PMID 33348538, 2020). "For patients with ESRD, intact PTH levels should be 150–300 pg/mL, according to the National Kidney Foundation Kidney Disease Outcomes Quality Initiative35." (PMID 32277134, 2020). "The target range of PTH levels for dialysis patients was suggested by the Kidney Disease Outcome Quality Initiative (K/DOQI) guidelines and the KDIGO guidelines based on studies of bone and mineral disorders in patients with CKD." (PMID 32423377, 2020). "The Kidney Disease Improving Global Outcomes Guidelines recommend PTH and bone‐specific alkaline phosphatase (BSAP) for the diagnosis of turnover type." (PMID 32490328, 2020). "The 2017 Kidney Disease Improving Global Outcomes (KDIGO) guideline suggests that persistent parathyroid hormone (PTH) elevations over ninefold the upper limit of normal should be considered an indication for surgical management." (PMID 31879808, 2019). "We established PTH target values of 100–300 pg/ml considering the Kidney Disease: Improving Global Outcomes guidelines in order to demonstrate the effect of FGF23 independent of PTH." (PMID 31651370, 2019). "In aggregate, our results demonstrate that DMP1 decreases FGF23 levels in CKD, independently of mode of administration, age, mouse strain, kidney disease progression, phosphate, or PTH levels." (PMID 31044094, 2019). "In the context of mineral metabolism and its derangements in renal disease, many of these enzymes are key for the normal release of parathyroid hormone (PTH)." (PMID 29495444, 2018).
Kidney Disease (continued). "According to The National Kidney Foundation Kidney Disease Outcomes Quality Initiative guidelines, the optimal ranges of intact PTH levels are 150–300 pg/mL (normal range 12–72 pg/mL) for stage V CKD HD patients." (PMID 30208594, 2018). "Historically, bone abnormalities in patients with kidney disease were attributed to alterations in PTH and 1,25 dihydroxyvitamin D [1,25(OH)2D]." (PMID 30460334, 2018). "In our “real world” observational study, patients that initiated cinacalcet had progressively increasing PTH levels with a median value above the Kidney Disease improving global Outcomes (KDIGO) guideline targets at the time of initiation." (PMID 29391567, 2018). "For animals with sub-clinical disease, such as early-stage kidney disease, variation in hormonal status (e.g. parathyroid hormone) or vitamin status (e.g. Vitamin D) can profoundly influence mineral uptake from the gut34." (PMID 29215022, 2017). "In 2009, a new PTH threshold 2–9 times that of the upper normal limit compared to the conventional PTH level of 150–300 pg/mL was suggested by the Kidney Disease Improving Global Outcomes (KDIGO) for CKD stage 5 patients." (PMID 28152049, 2017). "Overall, at 3 months after PTx, 82.4 % of all patients had PTH levels below 162 pg/mL (two times the upper reference limit, acceptable according to the Kidney Disease: Improving Global Outcomes [KDIGO] guidelines)." (PMID 27459979, 2017). "The occurrence of these long PTH fragments is probably frequent, mainly in patients with kidney diseases due to their decreased glomerular filtration rate." (PMID 27812604, 2016). "Multivariable analysis of the relationship between lung function variables and values of vitamin D or PTH were performed, with each analysis adjusted for age, sex, height, BMI, current smoking status, and kidney disease." (PMID 26398210, 2015). "Renal secondary HPTH occurs when PTH synthesis and secretion become excessive during kidney disease and is the result of increased secretion of PTH by each chief cell as well as the increased number of chief cells due to PTG hyperplasia." (PMID 23566108, 2013). "In the early stage of CKD, fibroblast growth factor 23 (FGF23) level increases before parathyroid hormone (PTH) and phosphate levels increase, and steadily increases with the progression of kidney disease." (PMID 23013306, 2012). "In CKD, fibroblast growth factor 23 (FGF23) level increases early before PTH and phosphate levels increase, and steadily increases with the progression of kidney disease." (PMID 23013306, 2012). "Patients with more advanced stages of renal disease are subject to oxidative stress; accordingly hormones like PTH are oxidized." (PMID 22792251, 2012). "While the maximum PTH level in the present cohort with asSpA was 119.4 pg/dL, extremely increased levels (up to tenfold of the current) were found in the previously studied patients with kidney disease." (PMID 41326868, 2025). "However, the Kidney Disease Outcomes Quality Initiative (KDOQI) 2003 guideline establishes target ranges for PTH levels in CKD stage 3–5D." (PMID 40429305, 2025). "Even more noteworthy is the association between baseline PTH levels and cardiovascular complications among populations without apparent renal disease." (PMID 38785509, 2024). "Preoperative PTH may be influenced by several variables including vitamin D sufficiency and renal disease." (PMID 38478048, 2024). "The rationale was that low BMD may be due to CKD-MBD (e.g., high PTH) and that lowering PTH is a safer and more appropriate therapy than an antiresorptive (Kidney Disease: Improving Global Outcomes KDIGOCKD–MBD Work Group, 2009)." (PMID 37342799, 2023). "In experimental studies, it has been determined that high hormone concentrations can affect the expression of the enzyme NO synthase because patients with more advanced stages of kidney disease present an inversely proportional relationship between the concentrations of NO and PTH." (PMID 36232497, 2022).
Kidney Disease (continued). "Clinical features that raise concern for parathyroid malignancy include serum calcium >14 mg/dL, PTH >5–10 times the upper limit of normal or PTH >500 pg/mL, palpable neck mass, concomitant skeletal, renal disease, and features of parathyroid crisis, e.g., altered mental status." (PMID 35326576, 2022). "Thus, for dialysis patients, the Kidney Disease Improving Global Outcomes (KDIGO) guidelines recommend a parathyroid hormone (PTH) level target of two to nine times the upper limit of normal." (PMID 35880645, 2022). "In male mice, adenine-induced CKD has been shown to create kidney disease with high PTH." (PMID 33891630, 2021). "However, one of the leading treatments for SHPT in advanced renal disease are the calcimimetics (cinacalcet and etelcalcetide), which target the CaSR directly and provide clinically significant reductions in PTH secretion." (PMID 31619668, 2019). "In order to prevent this change in CKD stages 3 to 5, the Kidney Disease Improving Global Outcomes (KDIGO) experts recommended that the serum parathyroid hormone (PTH) level should be maintained in the normal range of the assay, even if the optimal level is not known." (PMID 29912988, 2018). "Furthermore, the Kidney Disease: Improving Global Outcomes guidelines recommend maintaining the PTH levels of CKD stage V HD patients at 2- to 9-fold the upper normal limit." (PMID 30208594, 2018). "This is probably due to decreased insulin secretion in people with kidney disorders which might be due to metabolic acidosis, increased parathyroid hormone and decreased vitamin D level." (PMID 28497087, 2017). "Reasons for a picture with elevated calcitriol, normal 25-OH vitamin D, and minimally lowered PTH could be treatment with calcitriol (sometimes used in the treatment of parathyroid or kidney disease) or endogenous production of calcitriol." (PMID 26499069, 2015). "The bidirectional stimulatory effects of PTH and aldosterone may potentiate the risks of development and progression CV and bone, kidney disease in patients with PHPT." (PMID 22974443, 2012). "In haemodialysis patients with sHPT, cinacalcet treatment could increase the number of patients achieving National Kidney Foundation Kidney Disease Outcomes Quality Initiative targets (PTH, calcium, phosphate) compared to standard therapy." (PMID 18594867, 2008). "Furthermore, a weak but significant positive correlation (r = 0.413) was also found between age and PTH, which may indicate the complex role of adropin in the pathophysiology of kidney disease." (PMID 40128042, 2025). "Indeed, the conceptof CKD–mineral and bone disorder (CKD–MBD) appeared in the early 2000s,emphasizing the key role of kidney disease and the accompanying abnormalities incalcium, phosphate, hormonal (PTH), vitamin (D), and bone metabolism on theappearance of calcifications in the vessels." (PMID 39484140, 2024). "Moreover, resistance to PTH action can occur with progression of renal disease." (PMID 37730530, 2023). "Current Kidney Disease: Improving Global Outcomes (KDIGO) guidelines recommend iPTH target levels of 2-9 times the upper limit of normal for the assay, reflecting the increased risk with both low (adynamic bone disease) and high (high bone turnover disease) PTH levels." (PMID 34595186, 2021). "However, lynx with renal disease had very low PTH values (1.2 ± 0.7 pg/mL)." (PMID 27243456, 2016). "Thus in this stage of kidney disease, a normal iCa concentration with increased PTH concentration and normal-to-high serum phosphorus concentration may be observed." (PMID 23566108, 2013). "The Kidney Disease: Improving Global Outcomes (KDIGO) guidelines recommend monitoring serum levels of calcium, phosphate, PTH, and alkaline phosphatase activity beginning in CKD stage G3a." (PMID 40429305, 2025). "This level is selected following Kidney Disease Outcomes Quality Initiative (KDOQI) guidelines, which recommend a PTH level between 150 pg/ml and 300 pg/ml." (PMID 38681457, 2024).
Kidney Disease (continued). "As to the recommended PTH targets for CKD-MBD patients, the National Kidney Foundation's Kidney Disease Outcomes Quality Initiative (KDOQI) guideline published in 2003 suggests target ranges of PTH levels that are different in different stages of CKD." (PMID 39208984, 2024). "For example, the production of 1.25-OHD can be influenced by renal diseases, phosphorus and calcium can suppress 1.25-OHD synthesis and parathyroid hormone (PTH) can stimulate its synthesis." (PMID 36836729, 2023). "For biochemical abnormalities, the Kidney Disease Improving Global Outcomes (KDIGO) guidelines 2017 recommend regular monitoring of serum calcium, phosphate, parathyroid hormone (PTH) and alkaline phosphatase (ALP) starting from CKD stage 3." (PMID 37102048, 2023). "Increased levels of PTH and FGF-23 mediate increased phosphate excretion per functioning nephron in early stage renal disease." (PMID 35204237, 2022). "We hypothesized that treatments to reduce reactive oxygen species formation and reduce parathyroid hormone (PTH) levels would have additive beneficial effects to prevent cardiovascular calcification and deleterious bone architecture and mechanics before end‐stage kidney disease." (PMID 35309859, 2022). "On the basis of the 2017 Kidney Disease: Improving Global Outcomes (KDIGO) guidelines, the level of bone turnover can be classified according to the level of PTH." (PMID 34803931, 2021). "Clinicians participating in this study declared to take into account the latest kidney disease improving global outcomes (K-DIGO) guidelines on levels of Ca, P, PTH." (PMID 31330805, 2019). "The Kidney Diseases Outcome Quality Initiative (KDOQI) clinical guidelines for hemodialysis (HD) are a useful criteria which help to monitor serum Ca, P and parathyroid hormone (PTH) levels in CKD patients." (PMID 31565143, 2019). "These should incorporate predictors of fracture specific to kidney disease, for example, bone alkaline phosphatase (BSAP) or PTH." (PMID 30460334, 2018). "In CKD, as the renal disease advances, a decline in Klotho expression has been reported whereas FGF-23 expression increases progressively; high serum phosphate and PTH and low vitamin D levels accompany these changes." (PMID 30370270, 2018). "Our own classification statistics should improve as more patients have key metabolic lab values (PTH, vitamin D) recorded in the EHR, known to be abnormal early in the course of renal disease." (PMID 25431293, 2014). "In patients with SHPT, the targeted PTH reference value was ≤ 585 pg/mL (no more than nine times the upper limit of normal was chosen in agreement with Kidney Disease: Improving Global Outcomes guidelines)." (PMID 40244409, 2025). "Considering the AKI group, only 4 of 35 (11.4%) dogs had PTH concentrations overlapping those observed in dogs without kidney disease." (PMID 40005891, 2025). "For example, C3H/Hej mice develop adenine-induced kidney disease without elevated PTH and do not develop cortical porosity, while C57Bl/6 J mice, similar to this study, have high PTH and porosity development." (PMID 38505524, 2024). "Parathyroid hormone levels increased as kidney disease progressed in patients without DM (p = 0.03) and were higher in patients with T2DM." (PMID 36232497, 2022). "Due to the increase in OS in CKD, a proportion of PTH is oxidized in patients with kidney disease, which means that the hormone is not biologically active." (PMID 36232497, 2022). "In the present study, the obtained concentrations of PTH increased as the stage of kidney disease progressed in patients with and without DM." (PMID 36232497, 2022). "The majority of studies used a PTH-level reference range of 10–69 pg/ml for patients without kidney disease, whereas it varied across the studies with samples of patients on dialysis." (PMID 26010883, 2015).